CCL7 (C-C motif chemokine ligand 7)
Diseases named in the same sentence as CCL7 in open-access papers (continued):
Sharing a sentence is not in itself a finding about the gene and the disease.
colon carcinoma (9 papers, 2016 to 2022). "The migration assay was performed with CAFs ± CCL7-blocking antibody and CAFs that were treated with exosomes isolated from colon cancer cell lines." (PMID 33175885, 2020). "Here, the CCL7/CCR3 signaling axis has been described to promote colon cancer metastasis in a ERK-JNK-dependent manner." (PMID 31963450, 2020). "According to previous reports, CCL7 is known to be downregulated by miRNA let-7d, which is one of the miRNAs expressed by exosomal miRNA from the human colon cancer cell line sequencing in our experiment." (PMID 33175885, 2020). "Our results identified CCL7 as a chemokine upregulated in CT26 colon cancer cells cocultured with MSCs compared with CT26 in monoculture in vitro." (PMID 30764543, 2019). "On the other hand, in another study on colon cancer patients, CCL7 overexpression and its receptor expression was correlated with metastasis to the liver." (PMID 30764543, 2019). "Taken together, our data indicate that CCL7 can significantly stimulate CCR3 expression in colon cancer cells." (PMID 27167205, 2016). "Similar to these results, we also found that CCL7/CCR3 crosstalk induced EMT process in colon cancer cells." (PMID 27167205, 2016). "First, we found that CCL7 enhanced colon cancer cell proliferation and induced both cell invasion and cell migration in vitro." (PMID 27167205, 2016). "Between weeks 1 and 3, the mean volume of CCL7 overexpressing colon cancer tumors was higher than that of the control GFP expressing colon cancer tumors." (PMID 27167205, 2016). "To explore the function of CCL7 in colon cancer motility and invasiveness, we analyzed E-cadherin expression on the surface of HCT116 cells treated with or without recombinant CCL7 using FACS analysis." (PMID 27167205, 2016). "However, there are few studies on the mechanism of CCL7 in colon cancer bone metastasis, and few studies on the effect of osteoclastic precursor cells in the microenvironment of colon cancer bone metastasis." (PMID 35715847, 2022). "Furthermore, CCL7 levels were higher in liver metastasis of colon cancer than in primary colon cancer, and this CCL7 overexpression increased cell growth, migration, and invasion in in vitro and in vivo models." (PMID 34206004, 2021). "CCL7 also promoted colon cancer cell metastasis via CCR3 through both the ERK and JNK pathways." (PMID 34206004, 2021). "Colon cancer cell lines contained miRNA let-7d in secreted exosomes targeting the chemokine CCL7." (PMID 33175885, 2020). "Initially, our study focused on the crosstalk between mesenchymal stem cells (MSCs) and CT26 colon carcinoma cells and resulted in identifying CCL7 as a chemokine upregulated in CT26 colon cancer cells cocultured with MSCs, compared with CT26 in monoculture in vitro." (PMID 30764543, 2019). "Our current data showed that CCL7 enhanced the proliferation of colon cancer cells in vitro." (PMID 27167205, 2016). "In conclusion, our results imply that CCR3- correlated ERK-JNK activation may be a molecular link in the induction of metastasis by CCL7 in colon cancer cells." (PMID 27167205, 2016). "In this study, we also found that CCL7 enhanced proliferation of colon cancer cells." (PMID 27167205, 2016). "To determine whether CCL7 has direct effect on the proliferation of colon cancer cells, we performed both WST-1 assay (indirect method) and cell counting assay (direct method) for HCT116 cells." (PMID 27167205, 2016). "However, little is known about the molecular mechanism of CCL7-induced EMT signaling cascade in colon cancer." (PMID 27167205, 2016). "These compelling results reveal that CCR3 is a major activator of CCL7 induced cell invasion and migration, the major characteristics of EMT in colon cancer cells." (PMID 27167205, 2016). "To investigate the role of CCL7 in colon cancer cells, we established HCT116 and HT29 cell line that stably overexpressed CCL7 by lentiviral transduction." (PMID 27167205, 2016).
colon carcinoma (continued). "Third, we observed that CCL7 activated ERK and JNK signaling in MAPK pathways through CCR3 in colon cancer cells." (PMID 27167205, 2016). "This study is the first one focusing on metastasis via CCL7/CCR3 crosstalk and related signaling pathways in colon cancer." (PMID 27167205, 2016). "Evidence of such mechanistic interplay between CCL7/CCR3 and ERK–JNK cascade provides important insights into cell invasion and migration in colon cancer." (PMID 27167205, 2016). "The expression of CCL7 tended to be higher in rectal than colonic tumors by 1.8-fold (p = 0.086), without changes in the non-affected mucosa with respect to the tumor location." (PMID 34885960, 2021). "Furthermore, CCL7 also was regulated by MEK/ERK pathways in many cancers, such as colon cancer cells and Liver metastases." (PMID 32874132, 2020). "Also, the interaction between CCL7 and CCR3 has been shown to promote colon cancer cell metastasis via ERK-JNK signaling." (PMID 31419632, 2019). "These novel finding strongly suggest that suppressing oncogenic communication between CCL7 and CCR3 may be a potential therapeutic strategy for preventing human colon cancer metastasis." (PMID 27167205, 2016). "Thus, the objective of this study was to investigate CCL7-induced EMT signaling pathway and its role in the progression and metastasis of colon cancer." (PMID 27167205, 2016).
glioblastoma (9 papers, 2020 to 2024). The most malignant astrocytic tumor (WHO grade IV). "Since LDHA, CCL2 and CCL7 are genes encoding secreted proteins, we compared their protein levels in patient plasma showing that all of them were higher in glioblastoma patients than that in healthy controls, but such levels were not changed in meningioma patients." (PMID 38443336, 2024). "Here, we further identified that YAP1 activation promotes macrophage infiltration via direct transcriptional regulation of CCL2 and CCL7 in glioblastoma cells, consistent with the findings observed in liver cancer." (PMID 38443336, 2024). "Mechanistically, LDHA-lactate-directed ERK pathway activates YAP1 and STAT3 transcriptional co-activators to upregulate CCL2 and CCL7 in glioblastoma cells, which promote macrophage infiltration into the TME." (PMID 38443336, 2024). "Together, these findings suggest that YAP1 and STAT3 transcriptional co-activators contribute to LDHA/lactate–ERK axis-dependent CCL2 and CCL7 expression in glioblastoma cells." (PMID 38443336, 2024). "Moreover, plasma LDHA correlated positively with plasma CCL2 and CCL7 and intratumoral macrophages in glioblastoma." (PMID 38443336, 2024). "Moreover, treatment with EMφ EVs upregulated the levels of P-ERK, YAP1, P-STAT3, CCL2, and CCL7 in glioblastoma cells." (PMID 38443336, 2024). "In summary, our work reveals that glioblastoma cell glycolysis triggers the infiltration of macrophages into the TME via upregulating LDHA-regulated CCL2/CCL7, and reciprocally, macrophages promote tumor growth and survival via EVs delivering LDHA to glioblastoma cells." (PMID 38443336, 2024). "We also identify CCL2 and CCL7 as predictors of survival in human glioblastoma." (PMID 36685592, 2022). "The results indicated that the source of CCL5, CCL7, and CXCL1 in our experimental system was mainly MSCs, while CXCL16 was predominantly secreted by glioblastoma U251 cells." (PMID 39272976, 2024). "To further confirm the role of glioblastoma cell CCL2 and CCL7 in macrophage infiltration, we first employed shRNAs to deplete CCL2 and CCL7 in CT2A and GL261 cells." (PMID 38443336, 2024). "In summary, these results reinforce that the expression of CCL2 and CCL7 in glioblastoma cells/GSCs is regulated by LDHA and that glioblastoma cell CCL2 and CCL7 function as potent macrophage chemoattractants." (PMID 38443336, 2024). "In exploring the connection between LDHA and macrophage biology, we demonstrated that glioblastoma cell LDHA upregulates multiple downstream chemokines, most prominently CCL2 and CCL7, to trigger macrophage infiltration, consistent with previous work." (PMID 38443336, 2024). "Combined profiling and functional studies demonstrate that LDHA-directed ERK pathway activates YAP1/STAT3 transcriptional co-activators in glioblastoma cells to upregulate CCL2 and CCL7, which recruit macrophages into the tumor microenvironment." (PMID 37886538, 2023). "To confirm the role of LDHA in regulation of the YAP1/STAT3–CCL2/CCL7 signaling axis in vivo, we performed immunofluorescence for YAP1 and STAT3 in tumors and ELISA for CCL2 and CCL7 in plasma from control and LDHA-inhibited glioblastoma tumor-bearing mice." (PMID 38443336, 2024). "The decreased P-ERK, YAP1, P-STAT3, CCL2, and CCL7 in LDHA-depleted glioblastoma cells was rescued by the treatment with EMφ EVs, but not LDHA-depleted EMφ EVs." (PMID 38443336, 2024). "Clinical validations demonstrated that the intratumoral LDHA–YAP1/STAT3–CCL2/CCL7 signaling axis and plasma LDHA track with macrophage density and may function as potential biomarkers for glioblastoma patients." (PMID 38443336, 2024). "Moreover, bioinformatics analyses in TCGA glioblastoma dataset confirmed that LDHA, YAP1, STAT3, CCL2, and CCL7 positively correlated with each other and with macrophage signature in patient tumors." (PMID 38443336, 2024).
glioblastoma (continued). "To further investigate whether LDHA-regulated lactate contributes to this process, we treated LDHA-depleted glioblastoma cells with lactate and found that this treatment rescued the impaired signaling of P-ERK, YAP1, P-STAT3, CCL2, and CCL7 in shLdha CT2A cells." (PMID 38443336, 2024). "Moreover, plasma LDHA, CCL2, and CCL7 levels were not related to the status of recurrence, gender, age, and MGMT methylation in glioblastoma patients." (PMID 38443336, 2024).
hepatocellular carcinoma (9 papers, 2020 to 2025). A malignant tumor that arises from hepatocytes. "Taken together, TREM1 and CCL7 are the proven cancer-promoting factors of hepatocellular carcinoma." (PMID 38914803, 2024). "In conclusion, CCL7 derived from TREM1+ TAMs can promote hepatocellular carcinoma metastasis." (PMID 38914803, 2024). "Based on the median expression index of 4.0, determined by the IHC score for CCL7 protein expression levels in a cohort of 50 patients with hepatocellular carcinoma (HCC), the patients were categorized into two groups: CCL7‐strongly positive and CCL7‐weakly positive." (PMID 40062588, 2025). "Moreover, contrasting CCL7’s predominant activation of TGF-β-induced EMT in hepatocellular carcinoma, CAF-derived CCL7 in OSCC primarily operated through CCR1 activation and downstream signaling." (PMID 41430036, 2025). "Research on cervical squamous carcinoma cells, hepatocellular carcinoma, lung adenocarcinoma, and uveal melanoma shows that chronic hypoxia does not affect CCL7/MCP-3 expression due to the lack of an HRE sequence in the promoter region of the CCL7 gene." (PMID 32781743, 2020).
lung fibrosis (9 papers, 2020 to 2024). "Our data show that mice with Arrb1 deficiency in fibroblasts were protected from bleomycin-induced lung fibrosis, Arrb1-deficient fibroblasts promoted AEC2 proliferation, and Arrb1 deficiency in fibroblasts led to decreased Ccl7 expression." (PMID 38736470, 2024). "In mouse models of lung fibrosis, Ccl7 is produced during both FITC- and bleomycin-induced fibrosis, and Ccr2 deficiency has been shown to protect against fibrosis." (PMID 39768150, 2024). "In patients with systemic sclerosis, serum CCL7 levels correlate with the severity of pulmonary fibrosis." (PMID 39768150, 2024). "Intriguingly, lung fibrosis was efficiently inhibited in ATII cell-specific Ccl12 knockout mice, and the expression levels of CCL2 and CCL7 were decreased in BAL fluid obtained from these mice." (PMID 37524875, 2023). "CCR2 is the receptor of CCL2, CCL7, and CCL12, which plays an important role in the progression of pulmonary fibrosis." (PMID 36556326, 2022). "The elevated CCL2, CCL7, and CCR2 in the lung of the o-PF group suggest they are the important executors of pulmonary fibrosis in old rats, in addition to TGF-β." (PMID 36556326, 2022). "SARS-CoV-2 virus binds to angiotensin converting enzyme 2 (ACE2) and alters renin-angiotensin system activities, thus leading to enhanced inflammation (increased levels of VEGF, IP-10/CXCL10, MCP-3/CCL7, IL-6, IL-1, ROS etc.)and development of pulmonary fibrosis." (PMID 35139898, 2022). "In addition, CCL12 knockout mice were found to have a compensatory increase in the expression of CCL2 and CCL7 in lung tissue and bronchoalveolar lavage fluid, and CCL12 knockout did not protect mice from the formation of pulmonary fibrosis." (PMID 33176882, 2020).
rheumatoid arthritis (9 papers, 2010 to 2025). A chronic, systemic autoimmune disorder characterized by inflammation in the synovial membranes and articular surfaces. "CCL7 is also significantly upregulated in rheumatoid arthritis, activating the JAK2–STAT1 pathway through CCR1 to form an autocrine feedback loop." (PMID 41430036, 2025). "Elevated Ccl7 expression has been reported in various inflammatory conditions, including inflammatory bowel disease, rheumatoid arthritis, and multiple sclerosis." (PMID 39902039, 2024). "GA suppresses the expression of several proinflammatory mediators, such as IL-6, IL-1β, CCL2 and CCL7, in fibroblast-like synoviocytes from rheumatoid arthritis patients." (PMID 31026283, 2019). "Using in vitro and in vivo models, soluble syndecan-3 inhibited leukocyte migration in vitro in response to CCL7 and its administration in murine models of rheumatoid arthritis reduced histological disease severity." (PMID 31300004, 2019). "Most importantly, the expressions of key proinflammatory genes such as Il6, Vcam1, Ccl7, Mmp3, Mmp13, enhanced in rheumatoid arthritis and osteoarthritis, were reduced." (PMID 24199619, 2013). "CCR2 is normally involved in the infiltration of monocytes in inflammatory diseases such as rheumatoid arthritis and its ligands include CCL2, CCL7, and CCL8." (PMID 20976171, 2010).
liver fibrosis (8 papers, 2017 to 2025). "Over expression of TIMP-1 is associated whit liver fibrosis, while MMP-13 cleaves and inactivates CCL2, CCL7 and CXCL12 leading to reduction in chemotaxis, as well as to a decrease in the fibrosis process." (PMID 29040281, 2017). "Notably, it inhibited the expression of both CCL2 and CCL7, also known as monocyte chemotactic protein 3 (MCP3), which are upregulated in active HSC and cause a local inflammatory reaction during liver fibrosis." (PMID 41196648, 2025). "However, individual chemokine concentrations, such as CCL3, CCL7, CCL24 (eotaxin-2), Macrophage Migration Inhibitory Factor (MIF), and soluble TNF-α receptor 1, were positively associated with Schistosoma-related liver fibrosis." (PMID 30619332, 2018). "In conclusion, we found that emodin has inhibitory effects on liver fibrosis, which may be associated with reducing the Gr1hi monocytes infiltration by the inhibition of MCP-1 and CCL7." (PMID 29743924, 2018). "Our study also found that MCP-1 and CCL7 expression increased significantly during liver fibrosis, suggesting that MCP-1 and CCL7 may play important roles in liver fibrosis." (PMID 29743924, 2018).
pancreatic cancer (8 papers, 2013 to 2025). "At the transcript level, mRNA expression of Ccl2, Ccl7, Cxcl1, Cxcl3, and Csf2 was markedly downregulated in Ccn1‐deficient pancreatic tumors, whereas Cxcl5, Csf1, and Csf3 expression remained unchanged, and Ccl20 mRNA was elevated." (PMID 40287974, 2025). "Previously, we have demonstrated in a nude-mouse pancreatic cancer model that the recombinant H-1PVs encoding IL-2 or the chemokine MCP-3/CCL7 cause recruitment of activated NK and monocytes to the site of tumor, resulting in a strong antitumor response." (PMID 23902851, 2013). "The antitumor efficacy of parvovirus vectoring cyto/chemokines (IL-2, MCP-3/CCL7 and IP-10/CXCL10) was assessed in pancreatic cancer xenograft." (PMID 35686109, 2022).
pneumonia (8 papers, 2015 to 2025). An acute, acute and chronic, or chronic inflammation focally or diffusely affecting the lung parenchyma, caused by an infection in one or both of the lungs (by bacteria, viruses, fungi, or mycoplasma.). "We next assessed the contribution of IL-1β, CXCL1, CCL2, and CCL7 to the recruitment of neutrophils during S. pneumoniae pneumonia using specific neutralizing Abs administered intranasally." (PMID 25948816, 2015).
prostate carcinoma (8 papers, 2016 to 2024). A carcinoma that arises from epithelial cells of the prostate gland. "Although the effect of the CCR3/CCL7 axis appears predominant in the enhanced migration of prostate cancer cells, our work underlines that other chemokines and their associated receptors, might be involved in prostate cancer directed migration towards adipose tissue." (PMID 26756352, 2016). "We were able to identify two factors, namely E-selectin and the chemokine CCL7, which were upregulated in lymphatics in both breast and prostate cancer, representing two different cancer models with strong lymphatic metastatic involvement." (PMID 31963450, 2020). "Adipose tissues dissected from obese mice release more CCL7, and higher CCL7 expression promotes prostate cancer cell migration." (PMID 29915688, 2018). "In response to mechanical stimulation, PC3 prostate cancer cells secrete more pro-metastatic factors, including CCL7 and TGF-β, and PC3 cells adopt an osteoblast-like phenotype for bone colonization." (PMID 29915688, 2018). "A set of results confirmed the role of CCL7 in the migration of prostate cancer cells towards Ad-CM." (PMID 26756352, 2016). "Prostate cancer cells (PC-3 and Du-145) underwent chemotaxis in response to increasing doses of recombinant CCL7 and their migration was inhibited by CCL7 neutralizing polyclonal antibody (pAb) when Ad-CM was used as a chemoattractant." (PMID 26756352, 2016). "CCL7 can enhance the invasion and migration of prostate cancer, oral squamous cell carcinoma, and gastric cancer." (PMID 27167205, 2016). "These adipocytes secrete CCL7 and use of Ad-CM prepared from these cells supported prostate cancer cells migration in a CCR3-dependent manner." (PMID 26756352, 2016). "It is interesting to note that in contrast to prostate cancer, the other models have been previously reported secrete CCL7 (refs 29, 54)." (PMID 26756352, 2016). "Similar results were obtained with LNCaP and C4-2B, two less aggressive prostate cancer cell lines, highlighting the role of the CCR3/CCL7 axis in the chemotaxis of prostate cancer cells in response to adipocyte secretions." (PMID 26756352, 2016). "The migration of prostate cancer cells towards CM from these primary tissues also depended on the CCR3/CCL7 axis." (PMID 26756352, 2016). "We sought to assess the role of adipose tissue in the CCL7-directed migration of prostate cancer cells." (PMID 26756352, 2016). "In addition, the chemokine (C-C motif) ligand 7 (CCL7) is another factor that directs the migration of prostate cancer cells harboring its respective receptor, C-C chemokine receptor type 3 (CCR3), which is linked to poor prognosis." (PMID 39596205, 2024). "In an additional prostate cancer co-culture model, we could confirm a “metastatic specific” upregulation of E-selectin and CCL7 in LECs after interaction with the prostate cancer cell lines LNCAP (highly metastatic) and DU145 (weakly metastatic)." (PMID 31963450, 2020). "CCL5 belongs to the family of C-C chemokines as do CCL7, CCL8, and CCL21, which were also upregulated in prostate cancer lung metastases." (PMID 39146303, 2024). "We first verified that prostate cancer cells do not secrete this chemokine and that the inhibition of CCR3/CCL7 did not affect cell migration in response to 10% FCS." (PMID 26756352, 2016).